PRKD1 (protein kinase D1)
Diseases named in the same sentence as PRKD1 in open-access papers (continued):
Sharing a sentence is not in itself a finding about the gene and the disease.
autosomal dominant polycystic kidney disease (1 paper, 2021). Autosomal dominant form of polycystic kidney disease. "PRKD1 is associated with fibrogenesis in mouse models and human kidney diseases, such as autosomal dominant polycystic kidney disease." (PMID 34400910, 2021).
bladder urothelial carcinoma (1 paper, 2025). "In the bladder urothelial carcinoma (BLCA) protein-protein interaction network, the number of nodes was 118, and the number of edges was 108 (cutoff: 0.46), and PRKD1 gene had direct interaction with PKD1 and PKD2." (PMID 40984898, 2025). "Gene-gene interaction of PRKD1 in bladder urothelial carcinoma (BLCA) (cutoff: 0.46) showed co-expression of 77.42%, physical interaction of 10.96%, co-localization of 9.69%, predicted of 1.22%, genetic alteration of 0.47%, shared protein domains of 0.21 %, and pathway of 0.03%." (PMID 40984898, 2025).
cholangiocarcinoma (1 paper, 2025). A carcinoma that arises from the intrahepatic biliary tree (intrahepatic cholangiocarcinoma) or from the junction, or adjacent to the junction, of the right and left hepatic ducts (hilar cholangiocarcinoma). "In contrast, only two cancers, cholangiocarcinoma (CHOL) and liver hepatocellular carcinoma (LICH), showed significant PRKD1 upregulation." (PMID 40984898, 2025).
chromophobe renal cell carcinoma (1 paper, 2025). Chromophobe renal cell carcinoma is a rare subtype of renal cell carcinoma, originating from the intercalating cells of the collecting ducts and macroscopically manifesting as a well-circumscribed, highly lobulated, solid tumor that is usually diagnosed at an early stage. "For KICH, the GSE15641 dataset, comprising 23 normal kidney tissue samples and six chromophobe renal cell carcinoma samples, revealed 22,276 DEGs, with 15,223 downregulated and 7,053 upregulated; PRKD1 was downregulated (logFC = -0.4495177, adjusted p = 1.76e-04)." (PMID 40984898, 2025).
deafness (1 paper, 2019). An inherited or acquired condition characterized by the complete loss of the ability to hear from one or both ears. "Although a subset of genes that related to IHC machinery and deafness were found to be differentially expressed, a gradient of gene expression was indeed detected in Ocm, Pvalb, Prkd1, Fbxo32, Nme2, and Sncg, which may play putative roles in the Ca2+ buffering and survival regulation." (PMID 32038162, 2019).
developmental delay (1 paper, 2022). "In the case of patients with heterozygous mutations in the CDS of the PRKD1 gene, they suffered from not only CHDs but also intellectual disability, global developmental delay, hearing impairment, delayed language development, or microcephaly." (PMID 36568277, 2022).
Encephalopathy (1 paper, 2022). Encephalopathy is a term that means brain disease, damage, or malfunction.
endometrial cancer (1 paper, 2025). Primary or metastatic malignant neoplasm involving the endometrium (mucous membrane that lines the endometrial cavity). "The highest prevalence of PRKD1 mutations was observed in endometrial cancer, with 4.24% (24 patients) showing mutations and 0.18% (one patient) exhibiting deep deletions." (PMID 40984898, 2025).
Hydrocephalus (1 paper, 2023). Hydrocephalus is an active distension of the ventricular system of the brain resulting from inadequate passage of CSF from its point of production within the cerebral ventricles to its point of absorption into the systemic circulation. "Neither PRKD1 nor Kim1 have been associated with hydrocephalus previously." (PMID 38100419, 2023).
hypothyroidism (1 paper, 2023). Abnormally low levels of thyroid hormone. "In males, the top two child GRS SNPs were rs77165542, associated with BMR, adult BMI and self-reported hypothyroidism, and the rs61978655 SNP (situated in the PRKD1 gene) which is associated with BMR and adult BMI." (PMID 36952292, 2023).
intraepithelial neoplasia (1 paper, 2022). A precancerous neoplastic process that affects the squamous, glandular, or transitional cell epithelium without evidence of invasion. "Protein kinase D1 (PRKD1) reprograms pancreatic acinar cells to a ductal phenotype and drives progression to intraepithelial neoplasia (PanIN)." (PMID 35159011, 2022).
laryngeal carcinoma (1 paper, 2013). Carcinoma that arises from the laryngeal epithelium. "It seems worthy to prospectively validate PRKD1 expression as a laryngeal cancer prognostic marker, for routine clinical applications." (PMID 23950933, 2013). "It should be noted, however, that the differences observed in the expression of ACE2, FLOT1 and PRKD1 in favourable and unfavourable laryngeal carcinomas were not clear-cut in the array predictor, which may reflect the lack of direct genomic alterations within the corresponding gene sequences." (PMID 23950933, 2013).
leiomyosarcoma (1 paper, 2018). An uncommon, aggressive malignant smooth muscle neoplasm, usually occurring in post-menopausal women. "WNT9B (17q21.32), S phase entry blocker growth arrest specific 1 (GAS1) and serine/threonine protein kinase D1 (PRKD1) were expressed at low levels in PTSMT while the other analyzed tumor types showed higher levels, in particular, leiomyosarcomas." (PMID 29881541, 2018).
liver cancer (1 paper, 2016). An epithelial or non-epithelial malignant neoplasm that arises from the liver. "The mRNA levels of both Rrm2 and Prkd1 were higher in A/J than in A/J-12SM mice, but occurrence of liver cancer in A/J mice has not been reported." (PMID 27266874, 2016).
oral cancer (1 paper, 2025). "The PRKD1 E710D hotspot mutation and protein expression of PRKD1 and HH components (SHH, IHH, SMO, and GLI‐1) were detected in PAC regardless of tissue invasion, although HH proteins contributed to the morphogenesis of this rare oral cancer." (PMID 40930949, 2025).
prostate (1 paper, 2025). "Consistently, FRS2 knockdown has been reported to actas a repressor of protein kinase D1, leading to inhibition of prostate cancerprogression." (PMID 40834280, 2025).
rectal adenocarcinoma (1 paper, 2025). "Finally, the PRKD1 gene in rectum adenocarcinoma (READ) (cutoff: 0.78) showed co-expression of 87.71%, physical interaction of 5.87%, co-localization of 5.09%, genetic alteration of 0.61%, predicted of 0.41%, shared protein domains of 0.19%, and pathway 0.12% using GeneMANIA." (PMID 40984898, 2025). "PRKD1 expression remained unaltered in kidney chromophobe (KICH) and rectal adenocarcinoma (READ)." (PMID 40984898, 2025). "Finally, in the rectum adenocarcinoma (READ) protein-protein interaction network, the number of nodes were 118, the number of edges was 109 (cutoff: 0.78), and the gene interacting with PRKD1 was PKD2." (PMID 40984898, 2025).
Rett syndrome (1 paper, 2022). A severe neurodevelopmental disorder affecting the central nervous system.
squamous cell carcinoma (1 paper, 2013). A carcinoma arising from squamous epithelial cells. "The prognostic and biological significance of ACE2, FLOT1 and especially PRKD1 merits prospective validation, in order for these factors to possibly serve as independent prognostic markers for recurrence in patients with surgically resected squamous-cell carcinoma of the larynx." (PMID 23950933, 2013).
urothelial cell carcinoma (1 paper, 2025). "For BLCA, the GSE24152 dataset, which included seven normal kidney tissue samples and 10 urothelial cell carcinoma samples, identified 17,590 differentially expressed genes (DEGs), with 7,560 downregulated and 10,030 upregulated; PRKD1 was downregulated (logFC = -0.49774, adjusted p = 0.674)." (PMID 40984898, 2025).
tumor (63 papers, 2009 to 2025). "The tumor tissue samples harvested following 4 weeks of MT-1 treatment demonstrated increased PrKD1 protein levels associated with increased substrate phosphorylation of β-catenin (T-120) and Snail (S-11) compared to tumors from mice treated with vehicle-only control." (PMID 37568667, 2023). "PRKD1 itself is implicated in cell proliferation, cell motility, invasion, protein transport, and apoptosis, and would represent an interesting candidate in regard to tumor development and progression in CCF." (PMID 32927708, 2020). "Based on the percentage expression of cells in a given cluster, the log FC value, and the corresponding biological function, we ultimately identified ROR1 as a marker for tumor cells in TGCT and PRKD1 as a marker for MP3 tumor cells in D‐TGCT." (PMID 40126353, 2025). "Research suggests that PRKD1 can either inhibit or promote tumor growth, with outcomes influenced by genetic factors, signaling networks, and the surrounding tumor microenvironment." (PMID 40984898, 2025). "Concordantly, the results revealed a significantly higher percentage of PRKD1+ cells in D‐TGCT than in L‐TGCT and OA synovium, thereby confirming PRKD1 as a reliable marker for MP3 tumor cells." (PMID 40126353, 2025). "Among the many factors involved, protein kinase D1 (PRKD1) has garnered attention due to its complex role in tumor biology." (PMID 40984898, 2025). "Through these approaches, we aimed to elucidate the contribution of PRKD1 to tumor progression and clinical outcomes, thereby highlighting its potential as a biomarker and therapeutic target in human cancers." (PMID 40984898, 2025). "In PDA, a subgroup of PDA tumor cells demonstrates PRKD1 downregulation or inhibition together with increased EV secretion." (PMID 34207163, 2021). "A recent study has demonstrated that protein kinase D1 (PRKD-1) expression is significantly downregulated in PaCa tissues when compared to non-tumor tissues." (PMID 32878635, 2020). "miR-34a-mediated suppression of PRKD1 not only leads to the reduction of stemness and the suppression of tumor growth but also initiates apoptosis, with reduced drug resistance." (PMID 31861404, 2019). "In human HNSCC tissues, PKD1 was significantly down-regulated in localized tumors and metastases, and in patient-paired tumor tissues as compared to their normal counterparts, which was in part due to epigenetic modification of the PRKD1 gene." (PMID 30419840, 2018). "Since oxidative stress activates protein kinase D1 (PKD1) in tumor cells, we investigated the effect of excitotoxicity on neuronal PKD1 activity." (PMID 29273751, 2017). "Our PCR-based assay established to detect PRKD1 gene promoter methylation in formalin-fixed tissue also allowed us to determine the methylation status of PRKD1 specifically in ductal epithelial cells of normal breast and in tumor cells." (PMID 23971832, 2013). "As predicted for invasive cancer, we detected a high percentage of positive tumor cells for methylated PRKD1 promoter in both samples." (PMID 23971832, 2013). "We utilized our MSP-PCR method to analyze genomic DNA (gDNA) from fresh frozen tissues from patients with IDC and normal breast tissue adjacent to tumor for PRKD1 promoter methylation." (PMID 23971832, 2013). "Next, we compared PRKD1 promoter methylation in normal tissue adjacent to tumor, primary tumor and lymph node metastases from patients with IDC." (PMID 23971832, 2013). "In contrast, the percentage of tumor cells positive for methylated PRKD1 promoter significantly increased in samples from patients with ER+/HER2- IDC (average of 26.9%) and even more in HER2+ (average of 55.4%) or triple-negative (average of 59.7%) samples." (PMID 23971832, 2013). "Depending on the tumor context, PRKD1 exhibits either oncogenic or tumor-suppressive functions." (PMID 40984898, 2025). "Interestingly, PRKD1 exhibits both tumor-suppressive and oncogenic properties, depending on the specific cellular and molecular context." (PMID 40984898, 2025).
tumor (continued). "The shared biological processes influenced by PRKD1, including endocytosis, endothelial cell migration, and cell differentiation, suggest its significant contribution to maintaining cellular homeostasis and controlling tumor progression." (PMID 40984898, 2025). "Furthermore, knockdown of PRKD1 inhibits physiological angiogenesis and abolishes tumor angiogenesis in zebrafish." (PMID 32324784, 2020). "Therefore, we hypothesized that PRKD1 might also have a tumor‐promoting function in D‐TGCT and could potentially serve as a marker gene for MP3 tumor cells." (PMID 40126353, 2025). "However, the specific mechanism of PRKD1 remains unknown, and some research also indicates that PRKD1 has a contrary effect as a tumor suppressor or promoter in different cancer types." (PMID 31861404, 2019). "Since extraction of gDNA from fresh frozen tumor tissue sections can also contain gDNA from tumor-associated tissue (including stromal, fat and immune cells), we established an in situ MSP-PCR allowing the detection of methylated PRKD1 promoter in formalin-fixed, paraffin-embedded tissue." (PMID 23971832, 2013). "Emerging evidence suggests that cancer stem-like cell populations, characterized by markers such as CD44 and Protein kinase D1 (PKD1), contribute to intratumoral heterogeneity and tumor maintenance in PanNETs." (PMID 40648806, 2025). "Our findings indicate that hypermethylation of PRKD1 promoter regions in READ is significantly correlated with decreased expression levels, suggesting an epigenetic mechanism regulating its tumor suppressor function." (PMID 40984898, 2025). "Of the 16 kinases originally identified in the tumour dataset, 6 were also found to be differentially expressed in the cell line panel: AKT3, MYLK, PRKD1, AXL, NUAK1 and DCLK1." (PMID 33673003, 2021). "In line, our group has recently demonstrated that Protein kinase D1 (PRKD1) expression was significantly downregulated in many PDACs, compared with non-tumor tissue." (PMID 34638330, 2021). "PRKD1 inhibitor and miR-34a, which target PRKD1 through binding to the PRKD1 3′-untranslated region (UTR), suppress tumor growth and proliferation as well as drug resistance and induce apoptosis." (PMID 32426267, 2020). "For example, PRKD1 is expressed in normal ductal epithelial cells of the breast and inhibits EMT, which is a vital step for tumor cells to acquire the ability of invasion and metastasis." (PMID 31861404, 2019). "Using an animal model, we show that reversion of PRKD1 promoter methylation with the DNA methyltransferase inhibitor decitabine restores PKD1 expression and blocks tumor spread and metastasis to the lung in a PKD1-dependent fashion." (PMID 23971832, 2013). "Notably, Caucasian patients exhibited higher PRKD1 expression than African American patients in both BLCA and READ, suggesting possible racial disparities in tumor biology." (PMID 40984898, 2025). "Polymorphous adenocarcinoma is characterized by the PRKD1-E710D fusion gene, resulting from the rearrangement of the PRKD1 gene, yet it does not significantly affect tumor prognosis." (PMID 38966479, 2024). "Furthermore, pharmacologic reversion of PRKD1 methylation with the DNA methyltransferase inhibitor decitabine restored PKD1 expression and reduced tumor invasion and metastasis to lungs in an animal model." (PMID 37293129, 2023). "Indeed, via reduced phosphorylation of PRKD1 substrate cortactin, PRKD1− PDA tumor cells have an enhanced branching of actin filaments facilitating EVs loading and secretion." (PMID 34207163, 2021). "Notably, AKR1B1, CD36, ABCA1, PRKD1, OSBPL1A, and FABP3 showed varied expressions in specific cells, suggesting their significant roles in STAD carcinogenesis, further confirmed by elevated mRNA levels in tumor tissues via qRT-PCR." (PMID 38440405, 2024).